TRPC5 (transient receptor potential cation channel subfamily C member 5)
Diseases named in the same sentence as TRPC5 in open-access papers (continued):
Sharing a sentence is not in itself a finding about the gene and the disease.
nephrosis (1 paper, 2021). Pathological processes of the KIDNEY without inflammatory or neoplastic components. "In this study, we investigated the contribution of the TRPC5 channel in a PAN-induced nephrosis rat model." (PMID 34621762, 2021). "Taken together, these results revealed the relevance of TRPC5 channel inhibition in puromycin-aminonucleoside induced nephrosis models, highlighting the potential of this therapeutic strategy for patients." (PMID 34621762, 2021). "As expected, inhibition of TRPC5 channels by AC1903 was sufficient to protect podocyte cytoskeletal proteins and suppress proteinuria in PAN-induced nephrosis rats within a week." (PMID 34621762, 2021). "We first established that systemic administration of the TRPC5 inhibitor AC1903 was sufficient to protect podocyte cytoskeletal proteins and suppress proteinuria in PAN-induced nephrosis rats, an established model of podocyte injury." (PMID 34621762, 2021).
nicotine dependence (1 paper, 2009). Physical and psychological dependence on nicotine. "The association of rs7050529 (IVS3+286 of TRPC5) with CPD is notable as a closely related family member, TRPC7, was previously significantly associated with nicotine dependence." (PMID 19247474, 2009).
obstructive sleep apnea (1 paper, 2024). "TRPC5 has been found to be highly elevated in obstructive sleep apnea suggesting that calcium entry through this channel might play a role in the myocardial damage that occurs in obstructive sleep apnea." (PMID 38676362, 2024).
psoriasis (1 paper, 2025). An autoimmune condition characterized by red, well-delineated plaques with silvery scales that are usually on the extensor surfaces and scalp. "Moreover, TRPC5 is involved in the pathological development of keratinocytes and is inhibited in cells affected by psoriasis." (PMID 40723382, 2025). "Despite the fact that the information known about the role of TRPC5 in skin tumors is slim to none, studies show that TRPC5 plays a role in the pathological development of keratinocytes, e.g., in psoriasis." (PMID 40723382, 2025).
pulpitis (1 paper, 2022). Inflammation of the dental pulp. "A recent study implied that TRPC5 channels in odontoblasts may contribute to the generation of “inflammatory tooth pain” in teeth with pulpitis during direct cold stimulation of the dental pulp but not dentin surface." (PMID 36589456, 2022).
renal fibrosis (1 paper, 2025). A final common manifestation of a wide variety of chronic kidney diseases characterized by glomerulosclerosis and tubulointerstitial fibrosis. "Collectively, GQDs alleviate renal fibrosis by inhibiting TRPC5 activation and enhancing cell viability." (PMID 39739624, 2025).
retinal degeneration (1 paper, 2024). Degeneration of the retina. "For this purpose, we have considered the possibility that the TRPC1 and TRPC5 channels are involved in the maintenance of retinal calcium homeostasis, forming the heterodimer complex with special relevance during retinal degeneration due to RP." (PMID 39000357, 2024). "While TRPC1 expression and the TRPC1–TRPC5 interaction increased during retinal degeneration due to RP, the relative levels of TRPC5 did not change with age or due to photoreceptor degeneration." (PMID 39000357, 2024).
Sepsis (1 paper, 2024). Sepsis is defined as life-threatening organ dysfunction caused by a dysregulated host response to infection. "For instance, TRPC3 blockade has shown promise as a therapeutic intervention in mitigating sepsis development, while the interaction between TRPC5 and TRPC4 contributes to leukocyte accumulation and the release of inflammatory mediators." (PMID 38731999, 2024).
skin cancer (1 paper, 2025). "Considering these factors along with our findings, TRPC5 could be a potential diagnostic tool and drug target in skin cancer." (PMID 40723382, 2025). "Thus, drugs targeting the regulation of TRPC5 may be important for therapy against chemoresistance, which could also be relevant for skin cancer, especially irresectable or metastasized cases." (PMID 40723382, 2025).
Skin Tumors (1 paper, 2025). "Since this is the first research to investigate the expression of TRPC5 in common skin tumors, our study is primarily descriptive." (PMID 40723382, 2025).
Stroke (1 paper, 2020). Sudden impairment of blood flow to a part of the brain due to occlusion or rupture of an artery to the brain. "Other studies speculating a detrimental function of TRPC5 in neurological deficits following stroke had based on the activation of TRPC5 by oxidation, without experimentation in the stroke model." (PMID 33490083, 2020). "Since the TRPC4/C5 antagonists inhibit both TRPC4 or TRPC5 homomeric channels and TRPC1/C4 and TRPC1/C5 heteromeric channels, these data support the general idea that targeting TRPC1/C4/C5 channels can be beneficial to stroke therapy including post ischemic protection." (PMID 33490083, 2020).
type II diabetes (1 paper, 2023). "Also, TRPC5 was suggested as a key mediator for the central effects of the glucagon-like peptide-1 (GLP-1) receptor agonists liraglutide and semaglutide, used for type II diabetes and weight loss." (PMID 37631015, 2023).
ZIKV infection (1 paper, 2024). "Conversely, no significant alterations were observed in the expression of TRPC1, TRPC3, TRPC5, or TRPC6 upon ZIKV infection." (PMID 39009885, 2024). "However, AC1903, a specific TRPC5 inhibitor, and Pyr3, an antagonist for TRPC3/C6, did not exhibit protective properties in our cell model for ZIKV infection." (PMID 39009885, 2024).
cancer (35 papers, 2009 to 2026). A tumor composed of atypical neoplastic, often pleomorphic cells that invade other tissues. "Among these cold-sensitive channels, TRPC5 has been particularly associated with the initiation and progression of various cancers." (PMID 39309444, 2024). "Although abnormal TRPC5 expression has been linked to cancer progression and chemoresistance, its role in regulating gastrointestinal cancer metastasis remains unexplored." (PMID 39309444, 2024). "TRPC3 and TRPC6 have been implicated in DOX-mediated cardiotoxicity, whereas TRPC5 has been associated with P-glycoprotein-induced chemoresistance in cancer cells." (PMID 39594815, 2024). "In colon cancer, TRPC5 expression is upregulated both in cancer tissue and in metastatic lymph nodes, which is associated with poorer overall survival and metastasis-free survival." (PMID 36837670, 2023). "More recent studies have demonstrated that dysregulation of TRPC5 in cancer cells is highly associated with cancer progression, especially its chemoresistance." (PMID 37174704, 2023). "Abnormal expression of TRPC5 has been associated with cancer progression and chemoresistance." (PMID 31801263, 2019). "The TRPC5 channel has been largely associated with drug resistance in several cancers." (PMID 30884858, 2019). "Our previous studies have demonstrated that TRPC5 is associated with cancer chemotherapy." (PMID 28600513, 2017). "Thus, it appears that the factors upregulating TRPC5 expression may increase the risk of anticancer drug resistance in cancer patients." (PMID 37174704, 2023). "While TRPCs are known to be involved in cancer biology, the specific role of TRPC5 in solid tumors, including its potential role as a diagnostic marker, remains largely unexplored." (PMID 40723382, 2025). "Despite the limited data on TRPC5 expression in cutaneous tumors, evidence from other tissues indicates its involvement in cancer progression, supporting its potential role as a therapeutic target." (PMID 40723382, 2025). "Collectively, these results suggest that TRPC5 is functionally overexpressed in gastrointestinal cancer cells and likely contributes to cancer progression." (PMID 39309444, 2024). "Supporting these observations, IF staining in cancer cells and IHC staining in primary tumors confirmed significantly elevated TRPC5 protein levels in gastrointestinal cancer cells compared to normal cells." (PMID 39309444, 2024). "In this study, kaempferol was identified through its targeting of TRPC5, shedding light on its potential mechanism against cancer metastasis." (PMID 39309444, 2024). "Both in vitro and in vivo evidence suggests that the deletion and functional inhibition of TRPC5 can impede gastrointestinal cancer metastasis, highlighting TRPC5 as a potential therapeutic target for managing cancer metastasis." (PMID 39309444, 2024). "Consistent with observations in TRPC5-silenced cancer cells, ML-204 significantly inhibited the migration and invasion of MKN-45 and DLD-1 cells, as demonstrated by transwell, wound healing, and 3D invasion assays." (PMID 39309444, 2024). "Analysis using multiple databases revealed that TRPC5 plays a critical role in regulating cancer cell motility Subsequent experiments confirmed that TRPC5 enhances filopodia formation by activating the ATP/p-MLC/p-cortactin signaling axis." (PMID 39309444, 2024). "Potentiation by acidic pHe and involvement in HIF-1α regulation demonstrates the interest of cancer cells in keeping TRPC5 channels active and over-expressed, in order to promote cancer-specific hallmarks, in particular chemoresistance." (PMID 35806388, 2022). "TRP channels implicated in mechanotransduction mechanisms that regulate cancer cell migration, invasion and metastasis include, among others, TRPC1, TRPC5, TRPM2, TRPM7, TRPM4, TRPV2 and TRPV4." (PMID 36158191, 2022). "TRPA1 and TRPC5 perform an important role in transducing chemical nociceptive stimuli, but upregulated TRPA1 and TRPC5 reveal poor prognosis in cancers." (PMID 36045706, 2021).
cancer (continued). "Contrarily, six ion channels are overexpressed in cancers and promote the activity of Wnt pathway (TRPC5, TRPV4, TRPM4, TRPM8, P2RX7, and ASIC1a)." (PMID 33117152, 2020). "It has been shown that TRPC5 was essential for MDR1 induction in drug-resistant cancer cells, notably through activation of the transcription factor NFATc3." (PMID 30884858, 2019). "The data confirm the existence of adverse reaction to EA in mice and suggest that it depends on a combination of TRPC4 and TRPC5 which therefore overlaps partially with TRPC4-dependent cancer cell cytotoxicity." (PMID 30038709, 2018). "Since reprogramed energy metabolism to glycolysis was demonstrated to be the major mechanism of generating ATP and the major ATP source for Ca2+ efflux in cancer, we explored the potential mechanism of [Ca2+]i homeostasis in chemoresistance induction by TRPC5." (PMID 29463225, 2018). "Our previous data have also shown that drug-resistant cancer cells produce abundant p-glycoprotein via TRPC5-related Ca2+ signaling." (PMID 28600513, 2017). "We found that cancer cells transfected with TRPC5 shRNA showed attenuated autophagy with ADM exposure." (PMID 28600513, 2017). "The growth of TRPC5-knockdown cancer cells after ADM exposure was markedly less than in cells transfected with control shRNA." (PMID 28600513, 2017). "Despite this recommendation for caution, we conclude that TRPC4 and TRPC5 represent potentially attractive targets for cancer therapeutics." (PMID 27289383, 2016). "A special role for TRPC5 has been suggested in the development of resistance to cancer chemotherapy." (PMID 27289383, 2016). "In this work, we identified TRPC4 and TRPC5 as the cellular efficacy targets of englerin A which lead to growth inhibition in cancer cell lines." (PMID 26098886, 2015). "The implication of TRPC5 in the progression and chemoresistance of various cancers suggests, as in the case of TRPV2, that studying the effects of astringents on these channels may have important implications for oral oncology." (PMID 41586439, 2026). "As TRPCs are involved in the regulation of calcium interchange, dysregulated TRPC5 activation may lead to altered calcium levels in cancer cells." (PMID 40723382, 2025). "To determine whether TRPC5 modulates cancer cell motility via filopodia formation, we observed that ML-204 markedly suppresses MYO10-induced filopodia in MKN-45 and DLD-1 cells in a concentration-dependent manner." (PMID 39309444, 2024). "The active ingredient kaempferol, derived from Rhizoma Kaempferiae, acts as a natural TRPC5 inhibitor and has shown efficacy in suppressing cancer metastasis, laying the groundwork for its potential development as an anti-metastasis agent for clinical application." (PMID 39309444, 2024). "This led us to explore active TCM components that may inhibit TRPC5 function, with the goal of developing anti-cancer drugs targeting gastrointestinal cancer." (PMID 39309444, 2024). "In this study, TRPC5 is identified as a key factor in counteracting the metastasis of gastrointestinal cancer, suggesting that targeted inhibition of TRPC5 in cancer cells may present a viable therapeutic strategy." (PMID 39309444, 2024). "According to Johnson and Maggiora's principle of molecular similarity, which states "similar compounds exhibit similar properties," DISCOVERY STUDIO 4.0 and relevant literature were employed to identify small molecule inhibitors of TRPC5 from TCM for potential anti-cancer therapy." (PMID 39309444, 2024). "The thermo-sensory receptor, transient receptor potential channel 5 (TRPC5), a non-selective calcium ion (Ca2+)-permeable ion channel, has been implicated in cancer initiation and progression." (PMID 39309444, 2024). "EV carrying transmembrane glycoproteins present on the surface of cancer cells may stimulate other cells to produce proteins that break down the basal membrane of healthy cells, and EV carrying TRPC5 induces resistance to anthracycline in other cancer cells." (PMID 36359374, 2022).
cancer (continued). "TRPC5 is another TRP family member that enhances cancer progression." (PMID 36158191, 2022). "Up-regulated TrpC5 leads to a strong increase in intracellular calcium concentration [Ca], increased Wnt5a expression and nuclear translocation of β-catenin, leading to reduced cancer differentiation and increased cancer cell stemness." (PMID 35836256, 2022). "This resistance might be transferred to other cancer cells through the vesicles containing tumor specific TRPC5 and the introduction of the channel into other cells." (PMID 32872338, 2020). "In addition, we found that cancer cells transfected with TRPC5 shRNA lentiviral particles showed attenuated autophagy and tumor size with ADM exposure." (PMID 28600513, 2017). "Indeed, the role of TRPC5 in promoting chemoresistance in different types of cancer is well known." (PMID 35806388, 2022). "Furthermore, in breast cancer, TRPC5 may be transferred from resistant cancer cells to sensitive cancer cells via a vesicular shuttle." (PMID 30917547, 2019). "Mechanistic investigations further demonstrate that TRPC5 promotes filopodia formation in gastrointestinal cancer cells via the ATP/p-MLC/p-cortactin signaling axis, unveiling a novel pathway driving cancer metastasis." (PMID 39309444, 2024). "In particular, we discuss the roles of Piezo1/2, TRPC1, TRPC5, TRPM2, TRPM4, TRPM7, TRPV2, and TRPV4 in mechanosensing and cancer metastasis." (PMID 36158191, 2022). "Further analysis of cell lines revealed that EA is a potent activator of TRPC4 and TRPC5 channels and TRPC4 expression correlates with EA sensitivity of cancer cell lines." (PMID 35165752, 2022). "In the following section, we provide an overview of how Piezo1/2, TRPC1, TRPC5, TRPM2, TRPM4, TRPM7, TRPV2 and TRPV4 affect cancer cell behavior." (PMID 36158191, 2022). "(−)-Englerin A (EA), a potential novel anti-cancer drug, is a potent selective activator of classical transient receptor potential 4 and 5 (TRPC4, TRPC5) channels." (PMID 35165752, 2022). "Support of Ca2+ overload being a vulnerability for cancer is that TNBC cell lines with increased TRPC4 and TRPC5 showed increased sensitivity to the TRPC4 and TRPC5 activator englerin A (EA) compared to cell lines with reduced expression." (PMID 32046188, 2020). "The increased Ca2+ entry through the upregulated ion channel TRPC5, besides its effects on the expression of MDR genes, allows the activation of autophagy that protects cancer cells against cell death." (PMID 30917547, 2019). "EA is a remarkably potent activator of ion channels formed by Transient Receptor Potential Canonical 4 and 5 proteins (TRPC4 and TRPC5) and TRPC4 is essential for EA-mediated cancer cell cytotoxicity." (PMID 30038709, 2018). "In addition, the TRPC4 and TRPC5 channels might play a pathophysiological role in cancer cells." (PMID 30463370, 2018). "There are still few studies of TRPC4 and TRPC5 and TRPC4- and TRPC5-containing channels in cancer cell lines and even fewer on human cancer itself." (PMID 27289383, 2016). "Additionally, TRPC1, TRPC5, TRPM2, TRPM4, TRPM7, TRPV2 and TRPV4 can independently induce EMT in cancer cells." (PMID 36158191, 2022). "Interestingly, the plant derived compound Englerin A induces cytotoxicity in some cancer cell lines expressing TRPC4 and TRPC5 by enhancing channel activity; thus, increasing cytosolic Ca2+ and so Na+ concentrations." (PMID 32138386, 2020). "Not much is known regarding the importance of TRPC4 or TRPC5 in enhancing migration and invasion of cancer cells, although at least TRPC4 seems to have a role in proliferation and tumor formation." (PMID 32138386, 2020). "Given this, we hypothesized that TRPC5, as a non-selective Ca2+ channel, may be relevant to cancer cell motility and filopodia formation." (PMID 39309444, 2024). "Further investigation revealed that kaempferol did not alter TRPC5 protein levels in cancer cells." (PMID 39309444, 2024).
cancer (continued). "Because the most common cancer cell cytotoxic effect of EA requires TRPC4 and not TRPC5, the study suggests partial overlap of the potential anti-cancer effect and the adverse reaction of EA." (PMID 30038709, 2018).